H19 (H19 imprinted maternally expressed transcript)
Diseases named in the same sentence as H19 in open-access papers (continued):
Sharing a sentence is not in itself a finding about the gene and the disease.
steatosis (continued). "Fatty acids elevate the expression of H19 in hepatocytes and diet-induced fatty liver, and H19 overexpression might promote steatosis and increase lipid accumulation." (PMID 36552725, 2022). "Here, we found that H19 was up‐regulated in steatosis and high‐fat diet (HFD)‐induced NAFLD." (PMID 31809000, 2020). "The expression of H19 was increased by fatty acids in hepatocytes and in diet-induced fatty liver, and overexpression of H19 could promote steatosis and augment lipid accumulation." (PMID 31064820, 2019). "To investigate whether H19 could regulate hepatocyte steatosis, we examined the effects of H19 on lipid accumulation and TG secretion in both cell lines." (PMID 31064820, 2019). "Knockdown of H19 inhibited steatosis and TG secretion in FFA-induced hepatocytes." (PMID 31064820, 2019). "Another condition, non-alcoholic fatty liver disease (NAFLD), occurs when fat is deposited in liver, steatosis, and lncRNAs, including H19 and its co-regulated protein-coding partner, IGF2, may play important roles in this disease progression." (PMID 28933364, 2017). "H&E staining showed that downregulation of H19 in HuRhKO mice reduced WDSW-induced intra-acinar (lobular) inflammation, hepatocellular ballooning, and macrovesicular steatosis." (PMID 36224648, 2022). "Deletion of H19 or knockdown of PTBP1 abolished high-fat and high-sucrose (HFHS) diet-induced steatosis." (PMID 30148159, 2017). "We suggested that the protective activities of IL-22 on high-fat-diet-induced hepatocellular necrosis, injury, steatosis, ROS accumulation and mitochondrial dysfunction and the activation of AMPK-AKT-mTOR signaling were significantly inhibited by lncRNA H19 knockdown." (PMID 32483425, 2020). "H19 was up-regulated in NAFLD cell and mouse model, and overexpression of H19 could promote steatosis and lipid accumulation." (PMID 31064820, 2019). "H19 overexpression prevented whitening of BAT, reduced vWAT but not scWAT hypertrophy and development of steatosis in obese animals." (PMID 30190464, 2018).
cholangiocarcinoma (18 papers, 2016 to 2025). A carcinoma that arises from the intrahepatic biliary tree (intrahepatic cholangiocarcinoma) or from the junction, or adjacent to the junction, of the right and left hepatic ducts (hilar cholangiocarcinoma). "In this study, we revealed the potential pathway of H19 that is targeted by let-7a/let-7b, causing the partial inactivation of IL-6 in its mediated inflammatory responses triggered by oxidative stress in cholangiocarcinoma." (PMID 27809873, 2016). "H19 has been proven to be associated with the pathogenesis of cholangiocarcinoma, which may provide a potential therapeutic target." (PMID 34977037, 2021). "The lncRNA‐miRNA‐mRNA and circRNA‐miRNA‐mRNA networks centered on H19, hsa‐miR‐196b‐5p, hsa_circ_0025636, and hsa_circ_0057335 reveal pivotal regulatory axes in the tumorigenesis and progression of cholangiocarcinoma." (PMID 40304434, 2025). "In cholangiocarcinoma, oxidative stress can also upregulate the expression of lncRNA H19 and lncRNA HULC." (PMID 37686677, 2023). "In cholangiocarcinoma, aberrant expression of H19 has been shown to promote proliferation and invasion through inflammatory and oxidative stress pathways in vitro." (PMID 35573683, 2022). "Bioinformatic analysis based on the TCGA and GEO databases found that H19 is a hub gene in cholangiocarcinoma." (PMID 34977037, 2021). "For example, H19 sponges let7a/let7b then mediate oxidative stress-induced IL-6 expression in cholangiocarcinoma." (PMID 33193379, 2020). "H19 sponges let7a/let7b then mediate oxidative stress-induced IL-6 expression in cholangiocarcinoma." (PMID 33193379, 2020). "Diagnostic value of lncRNAs for Cholangiocarcinoma: HULC(b), H19(c), LPAL2(d), C3P1(e), AC005550.3(f), APOC1P1(g), PVT1(h),and sensitivity: Sen." (PMID 30305026, 2018). "Others that are increased in HCC and cholangiocarcinoma, such as H19 which drives cell growth and invasion, was found to be decreased in FLC (Δlog2 = −3.66 padj = 1.39 × 10−9)." (PMID 29535801, 2018). "Additionally, H19 was found to promote Bcl-2 expression by downregulating miR-612 expression, which promoted cholangiocarcinoma." (PMID 34977037, 2021). "For example, whilst overexpression of the lncRNA H19 promotes cholangiocarcinoma cell growth under oxidative stress conditions, in pituitary tumors H19 has been found to act as a tumor suppressor lncRNA and inhibits the ability of cells to respond to metabolic stress." (PMID 32266130, 2020). "A recent study shows it upregulated long non-coding RNAs H19 and HULC sponging let-7a/let-7b and miR-372/miR-373 to regulate cholangiocarcinoma cell migration and invasion." (PMID 35579449, 2022). "Our previously study reported that H19 and HULC, activated by oxidative stress, promote cell migration and invasion in cholangiocarcinoma through a ceRNA manner." (PMID 30305026, 2018). "Moreover, H19 is a biomarker for diagnosis of cholangiocarcinoma with high sensitivity and specificity and H19 can sponge Let-a/b, miR-372 and miR-373 to enhance IL-6 production, CXCR expression and tumor-related inflammation, and malignant behaviors of cholangiocarcinoma." (PMID 32272875, 2020).
Insulin resistance (18 papers, 2012 to 2025). Increased resistance towards insulin, that is, diminished effectiveness of insulin in reducing blood glucose levels. "Currently, there is little research on the mechanism of insulin resistance in the liver regarding H19; only associations regarding expression and methylation status have been characterized." (PMID 28933364, 2017). "Further studies are needed to confirm whether growth restriction in association with premature pubarche and insulin resistance is a specific manifestation of loss of IGF2 expression through IGF2/H19 loss of methylation." (PMID 22646060, 2012). "In this study, we focused on three lncRNAs: MALAT1, MEG3 and H19, due to their previously reported roles in regulating glucose metabolism, insulin resistance, inflammation and antioxidant response." (PMID 39765830, 2024). "Our analysis further clarifies the role of H19 in lipid metabolism in skeletal muscle and its connection to insulin resistance." (PMID 33115498, 2020). "Our data suggest that overexpression of H19 ameliorates insulin resistance by reducing ectopic lipid accumulation in skeletal muscle." (PMID 33115498, 2020). "Another study which showed a similar alteration in the Igf2/H19 ICR upon maternal low-protein diet also illustrated insulin resistance and increased adipose expansion in offspring, implicating modifications in Igf2/H19 methylation in adipose growth." (PMID 32494846, 2020). "Up-regulation of H19 ameliorated glucose intolerance and insulin resistance of db/db mice, and was accompanied by amelioration of ectopic lipid accumulation in skeletal muscle and liver." (PMID 33115498, 2020). "Collectively, these results indicate that elevated H19 levels ameliorate glucose intolerance and insulin resistance in db/db mice." (PMID 33115498, 2020). "H19 overexpression in db/db mice inhibited lipid ectopic deposition in skeletal muscle, meanwhile improved glucose intolerance and insulin resistance as compared with control db/db mice treated with ad-GFP." (PMID 33115498, 2020). "Downregulation of H19 in diabetic muscle limits let-7 sequestration, subsequently increasing inhibition of the pathway and promoting insulin resistance." (PMID 28933364, 2017). "H19 has been shown to regulate glucose intolerance and insulin resistance, but studies have mainly focused on muscle and the pancreas." (PMID 28933364, 2017). "There is also significant evidence that H19 is important in other tissues, such as insulin resistance in muscle and insulin production in the pancreas due to glucose intolerance." (PMID 28933364, 2017). "Furthermore, insulin resistance and glucose intolerance in male offspring born of GDM pregnancies have been linked to DNA hypermethylation-related downregulation of H19, as well as IGF2, which originate from the same imprinted locus." (PMID 39765830, 2024). "Second, the decrease in lncRNA H19 expression is closely related to insulin resistance." (PMID 37344807, 2023). "In summary, we found that the expression level of H19 was downregulated in the skeletal muscle of obese and diabetic mice, and up-regulation of H19 ameliorated insulin resistance and glucose intolerance due to its ability to promote fatty acid oxidation and reduce ectopic lipid accumulation." (PMID 33115498, 2020). "Interestingly, a high-fat diet downregulates muscle H19 in mice, and a high-fat diet and inflammation are key contributors to type-2 diabetes and insulin resistance." (PMID 33071823, 2020). "As a consequence, H19 overexpression promotes hepatic glucose production and insulin resistance." (PMID 31191327, 2019). "Therefore, it would be interesting to explore whether the decrease in lncRNA H19 expression contributes to the insulin resistance in that condition." (PMID 37344807, 2023). "We show that H19 regulates the levels of HDAC6 within the cell and this regulation consequently determines IRS1 levels and insulin resistance in the skeletal muscle." (PMID 35842608, 2022).
Insulin resistance (continued). "In line with our current findings and previous reports on GDM, reduced H19 expression has been observed in serum samples and serum-derived exosomes of patients with T2DM, as well as in T2DM skeletal muscles and in animal models with induced insulin resistance." (PMID 39765830, 2024). "Our case of growth restriction, premature pubarche and insulin resistance in the absence of body asymmetry or other features of SRS adds to the expanding phenotype of IGF2/H19 methylation abnormalities." (PMID 22646060, 2012).
neuroblastoma (18 papers, 2005 to 2024). Neuroblastoma (NB) is the most common solid, extracranial childhood tumor. "Currently, the lncRNA H19 has been implicated in the progression of PD as it is down-regulated in neuroblastoma cells in a PD mouse model." (PMID 39456775, 2024). "Further, administration of metformin during I/R injury in Neuro2a cells, another neuroblastoma cell line, was shown to reduce the expression of H19 and Rho-associated protein kinase 2 (Rock2), which protects from cellular damage." (PMID 35946958, 2022). "In the present study, we found the H19 gene rs3024270 C>G polymorphism was associated with neuroblastoma susceptibility in females." (PMID 30890582, 2019). "Here we conducted a six-center hospital-based case-control study aiming to investigate the association between SNPs within the H19 gene and neuroblastoma risk." (PMID 31772668, 2019). "Findings from this study excluded the participation of lncRNA H19 gene SNPs in the risk of neuroblastoma." (PMID 31772668, 2019). "Our study serves as a basis for future replication studies in independent populations or for functional studies of lncRNA H19 gene SNPs in neuroblastoma risk." (PMID 31772668, 2019). "Given that polymorphisms in the lncRNA H19 gene are observed in several types of human malignancies, there likely to be similar events that contribute to the pathogenesis of neuroblastoma." (PMID 31772668, 2019). "We further carried out stratified analysis to analyze the association between H19 gene polymorphisms and neuroblastoma susceptibility under different subtypes including age, gender, tumor sites, and INSS stages." (PMID 31772668, 2019). "We have previously conducted an initial investigation of how H19 gene SNPs (rs2839698, rs3024270, and rs217727) regulate the risk of neuroblastoma in Chinese population." (PMID 31772668, 2019). "We hypothesize that single nucleotide polymorphisms (SNPs) in the H19 gene might predispose to neuroblastoma." (PMID 31772668, 2019). "Given that lncRNA H19 gene is critical in carcinogenesis, better understanding is needed of how lncRNA H19 gene SNPs might impact neuroblastoma risk." (PMID 31772668, 2019). "Our study provides new evidence that the rs3024270 C>G polymorphism in the H19 gene might be involved in the development of neuroblastoma." (PMID 30890582, 2019). "In this study, we investigated whether lncRNA H19 gene polymorphisms were involved in the risk of neuroblastoma in Chinese population using individuals from six centers." (PMID 31772668, 2019). "Herein, we performed a two-center hospital-based case–control study using data from 393 neuroblastoma patients and 812 control subjects to evaluate the association between the H19 gene rs2839698, rs3024270, and rs217727 polymorphisms and neuroblastoma risk in Chinese children." (PMID 30890582, 2019). "Here, we genotyped three SNPs (rs2839698 G>A, rs3024270 C>G, rs217727 G>A) from H19 gene in a Chinese population (700 subjects with neuroblastoma and 1516 control subjects) enrolled from six hospitals and examined the effect of individual and combined SNPs on the risk of neuroblastoma." (PMID 31772668, 2019). "In vitro experiments found that H19 inhibits apoptosis in neuroblastoma cells treated with membrane-permeable peptide (MPP) by regulating miR-585-3p." (PMID 39456775, 2024). "A study suggests that H19 can modulate PTEN/AKT3 signaling by acting as a ceRNA for miR-19a-3p in neuroblastoma cells, thus aggravating cerebral I/R injury." (PMID 35946958, 2022). "The lncRNA H19 is associated with PD progression; lncRNA H19 inhibits neuronal apoptosis in MPTP-induced PD mice and MPP+ treated neuroblastoma cells by regulating the miR-585-3p/PIK3R3 pathway." (PMID 34421536, 2021). "H19 is reported to be associated with multiple cancers such as LC, GC, CRC, pancreatic cancer (PC), ovarian cancer (OC), neuroblastoma (NB), and bladder cancer." (PMID 31480503, 2019).
neuroblastoma (continued). "Further functional studies on rs3024270 and studies with larger populations and different ethnicities would be valuable to clarify the role of H19 SNPs in neuroblastoma." (PMID 30890582, 2019). "Depolarization by treating with 100 mM KCl for 5 min resulted in the undulating phosphorylation of GSK‐3[beta] at Ser‐9 in SH‐SY5Y human neuroblastoma cells, in H19 −7/IGF‐IR rat embryonic hippocampal cells, and in PC12 rat pheochromocytoma cells." (PMID 28661005, 2018). "The results obtained from in vitro and in vivo experiments showed that H19 was upregulated following ischemic reperfusion injuries in the ischemic penumbra of animals, as well as in the neuroblastoma cell after oxygen-glucose deprivation and reperfusion (OGD/R)-induced injury." (PMID 33541284, 2021). "In conclusion, here we failed to provide the possibility of lncRNA H19 gene SNPs in predicting neuroblastoma risk." (PMID 31772668, 2019). "In the stratified analysis, no relation of H19 SNPs with the susceptibility of neuroblastoma patients, the origin of the tumor and the clinical stage of the tumor were found." (PMID 30890582, 2019). "Conclusions obtained here represent an important extension of our understanding of how H19 gene polymorphism is not relevant to neuroblastoma risk." (PMID 31772668, 2019). "Our results showed that none of the H19 gene polymorphisms contributed to the risk of neuroblastoma." (PMID 31772668, 2019). "In addition, two studies showed H19 gene rs2839698 polymorphism did not confer susceptibility to neuroblastoma in Chinese children." (PMID 32207861, 2020). "As expected, H19 has very strong ASE in almost all normal and tumor samples, whereas ASE of KIF1B is observed exclusively in neuroblastoma samples." (PMID 35246212, 2022). "To illustrate the utility of comparing normal and tumor tissues, we examined ASE for a well-established imprinted gene, H19, and for a tumor suppressor gene, KIF1B, which is located on chromosome 1p and is frequently deleted in neuroblastoma." (PMID 35246212, 2022). "John T. Powers (Dell Medical School at the University of Texas at Austin) gave an overview of the mechanisms of let-7 disruption in neuroblastoma and showed that multiple isoforms of let-7 agonist H19 long noncoding RNA (lncRNA) are highly expressed in MYCN non-amplified neuroblastoma." (PMID 37016725, 2023).
intrauterine growth restriction (17 papers, 2010 to 2025). "Plagl1 was previously shown to regulate expression of Cdkn1c, Igf2, H19, and Dlk1 and to belong to a subset of IGs that control embryonic growth and differentiation, and loss of Plagl1 function resulted in intrauterine growth restriction." (PMID 36437415, 2023). "The main phenotype of SRS is severe intrauterine growth restriction (IUGR) that could be caused by a reduction in IGF2 transcription as a result of a loss of methylation at the H19 DMD." (PMID 20617174, 2010). "Specifically, LINC03097 (ENST00000527727) appeared associated with fetal growth restriction (FGR), and H19 (ENST00000415029) with placenta accreta." (PMID 40870007, 2025). "The hypomethylation of H19 was described in intrauterine growth restriction which, in turn, would affect the biological potential of fetal growth." (PMID 37810933, 2023). "Significant differential methylation changes in the promoter region of H19 were reported in a multigenerational model of intrauterine growth restriction (IUGR)." (PMID 31849831, 2019). "Future studies may build on the results of this study to elucidate the role that the IGF2 and H19 genes play in the pathophysiology of adverse pregnancy outcomes, for example, intrauterine growth restriction." (PMID 39330587, 2024). "Thus, synthetic PIF`s role on H19 modulation in intrauterine growth restriction models is currently investigated but beyond the scope of this manuscript." (PMID 28704412, 2017). "However, there have been a few case reports of hypomethylation of H19 DMR associated with either hemi-hypertrophy alone or milder intrauterine growth restriction and post natal growth restriction associated with a prominent forehead and triangular facies as the only clinical signs." (PMID 22646060, 2012). "In mice, ART treatment resulted in small changes in methylation of control-region CpGs for H19, IGF2R, and PEG3, altered expression of these genes, and intrauterine growth restriction (IUGR)." (PMID 36142363, 2022). "The epigenetic modulation of IGF2/H19 during human development was marked in 60 normal and 66 idiopathic IUGR (Intrauterine Growth Restriction) pregnancies." (PMID 22319250, 2011).